PDHA1 (pyruvate dehydrogenase E1 subunit alpha 1)
Diseases named in the same sentence as PDHA1 in open-access papers (continued):
Sharing a sentence is not in itself a finding about the gene and the disease.
tumor (continued). "The double knockout of Pten and the major subunit of PDC, PdhA1, suppressed the tumor growth, which was accompanied by lower levels of TCA cycle activities and fatty acid synthesis." (PMID 34948229, 2021). "It has been reported that the expression of PDHA1 is abnormal in a variety of tumors, and it is closely related to tumor invasion, drug resistance, and prognosis by affecting tumor cell glucose metabolism." (PMID 35223866, 2021). "Loss of PDHA1 has been shown to decrease mitochondrial OXPHOS and promote aerobic glycolysis in tumor cells and promotes Warburg effect." (PMID 35004842, 2021). "Consistent with the in vitro experiments, HsA decreased the phosphorylation of PDHA1 in allograft tumor tissues in a dose-dependent manner." (PMID 33318678, 2020). "Conversely, the induction of SIRT3 was able to efficiently reduce tumor proliferation via an anti-Warburg effect mediated by the HIF1α/PDK1/PDHA1 pathway." (PMID 32138158, 2020). "We observed significantly higher TUNEL+ signals, which correlated with a reduced p-PDHA1 level in DIC-treated tumor samples, when compared to samples from the control or vehicle group." (PMID 28617852, 2017). "To understand the molecular mechanisms underlying DIC-induced tumor inhibition, we first measured the protein levels of PDK1, PDHA1, and p-PDHA1 in xenografts by western blot." (PMID 28617852, 2017). "Conversely, low PDHA1 expression in tumor cells may compel cancer cells to rely on glycolysis, leading to the production of substantial amounts of lactic acid and the formation of an acidic microenvironment." (PMID 41050056, 2025). "Furthermore, by using ST, the study demonstrated significant overexpression of metabolism-related genes (e.g., HK2, PDHA1, and CS) in tumor regions, further supporting the critical role of LSM1 in regulating tumor energy metabolism." (PMID 40867511, 2025). "It has been demonstrated that PDHA1 may promote tumour immune escape in certain tumours by regulating metabolism, affecting the efficacy of immunotherapy." (PMID 41050056, 2025). "Low PDHA1 expression in immune cells may maintain persistent immune cell activity in the tumour microenvironment by reducing mitochondrial oxidative phosphorylation and avoiding immune depletion due to excessive metabolic stress." (PMID 41050056, 2025). "Furthermore, CRISPR/Cas9-mediated double PDHA1/OGDH knock-down significantly reduced CD8+ T cell intra-tumoral motility as assessed using tumor slice derived from the BXPC3-NSG model." (PMID 38467616, 2024). "In addition, the results revealed the oncogenic role of PDHA1 in NB cells as well as the correlation between PDHA1 expression and tumor stages and NK cell infiltration in NB." (PMID 38012558, 2023). "On the other hand, mutations or deletions of the PDHA1 gene have also been found, suggesting that PDHA1 may act as a potential tumor suppressor gene." (PMID 37006250, 2023). "PDHA1 seems to have a paradoxical role in regulating tumour growth and metastasis." (PMID 37056926, 2023). "Taken together, we could speculate that the PDHA1-mediated cuprotosis process might promote tumor TME immune cell infiltration, thus enhancing the intratumoral antitumor immune response." (PMID 37006250, 2023). "As a crucial gene in the glucose metabolism reprogram of tumor cells, there is growing evidence that PDHA1 might act as a prognostic and immune-related biomarker and negatively associated with immune cell infiltration in TME." (PMID 37006250, 2023). "Recent studies have demonstrated that PDHA1 phosphorylation could promote tumor migration ability and therapeutic resistance by suppressing its PDH activity." (PMID 36003495, 2022). "This suggested that PDHA1 may be a potential biomarker for predicting the prognosis of tumor patients." (PMID 36003495, 2022). "The inactivation of PDHA1 promotes tumor glycolysis by downregulating the PDC activity." (PMID 36003495, 2022).
tumor (continued). "Third, we found the double-edged roles of PDHA1 as oncogenes or tumor suppressors in different cancers, which might be due to the different origins of cancer cells and the tumor heterogeneity." (PMID 36003495, 2022). "In the Human Protein Atlas database, the expressions of GLS, MTF1 and PDHA1 in tumor tissues were lower compared with those in normal tissues, while the expressions of DLAT and PDHB were significantly higher in tumor tissues compared with those in normal tissues." (PMID 36620594, 2022). "We further explored the phosphorylation of PDHA1 between normal and primary tumor tissues." (PMID 36003495, 2022). "DLD, LIAS, and PDHA1 had the highest expression in tumor cell-enriched region (PanCK-expressing)." (PMID 36618352, 2022). "Furthermore, the expression level of PDHA1 has been observed to correlate with the tumor immune microenvironment, and it may influence immune cell infiltration and tumor immune escape mechanisms." (PMID 41050056, 2025). "For instance, the deacetylase SIRT3 acts as a tumor suppressor in several cancer cells and contributes in deacetylating PDHA1, a subunit of the pyruvate dehydrogenase complex (PDC), thereby inducing its activity and causing an anti-Warburg effect via the HIF1alpha/PDK1/PDHA1 pathway." (PMID 37614745, 2023). "In our study, we found that PDHA1 might act as a tumor suppressor in CRC." (PMID 37006250, 2023). "In addition, the PDHA1 gene is involved in regulating the oxidative stress response of tumor cells, enabling them to acquire stronger antioxidant capabilities and survival advantages, thereby promoting tumor cell growth and metastasis." (PMID 37006250, 2023). "Prostate conditional Pten-null mice, knocked-out for PDHA1 expression in the prostate, displayed growth inhibition of prostate cells, and pharmacological inhibition of PDH activity in prostate Pten-null mice and in human PCa cells caused tumor and cell growth inhibition." (PMID 35692804, 2022). "Therefore, increased PDHA1 might promote the response to immunotherapy by inhibiting regulate T cell infiltration in the tumor microenvironment." (PMID 36518756, 2022). "Thus, we explored the PDHA1 genetic alterations in human tumor samples." (PMID 36003495, 2022). "Notably, we showed that increased phosphorylation of PDHA1 S232 is also present in human tumours, reinforcing the importance of this finding and the usefulness of integrated ohmics approaches to reveal molecular changes with potential impact for clinical outcomes." (PMID 29191787, 2018). "When dataset was expanded with GTEx data, a similar pattern was observed for most genes, although LIAS, PDHA1, and PDHB showed downregulation in tumor tissues." (PMID 40410601, 2025). "Paired comparisons further confirmed the upregulation of FDX1, DLAT, PDHA1, GLS, and CDKN2A in tumor samples." (PMID 40410601, 2025). "Inhibition of PDHA1 has been shown to decrease mitochondrial OXPHOS and promote tumor aerobic glycolysis in tumor cells, while an opposite effect was reported for PDHA1 overexpression." (PMID 38429887, 2024). "We found that FDX1, DLD, PDHA1, MTF1, GLS, and CDKN2A showed differential expression levels between normal and tumor tissues." (PMID 37711156, 2023). "Compared with adjacent non-tumor tissues, CDKN2A, DLAT, and PDHA1 protein expression was upregulated in HCC tissues." (PMID 38078880, 2023). "The expression level of CRGs with CNV amplification was higher in CRC samples compared to normal samples (e.g., GLS and PDHA1), while the expression level of LIAS was relatively decreased in tumor samples." (PMID 37006250, 2023). "Thioctyl has the ability to target DLAT, PDHA1, and PDHB, which in turn can modulate tumor progression by influencing diverse metabolic pathways." (PMID 38114959, 2023). "The phosphorylation at Ser293, Ser300 and Ser232 residues on PDHA1 decreases PDC activity and contributes to tumour metabolic reprogramming toward glycolysis in hypoxia, by inhibiting acetyl-CoA formation and the entry in the TCA cycle." (PMID 37875162, 2023).
tumor (continued). "The genes PDHA1 and PDHB, both part of the pyruvate dehydrogenase complex, are reported to influence oxidative phosphorylation, tumor growth, metastasis, and glycolysis regulation." (PMID 37239150, 2023). "The PDAC patients with higher expression levels of PDHA1, LIPT1, LIAS, and DLD, or lower expression levels of DLAT, in their tumor tissues had a better prognosis than their counterparts (p < 0.05)." (PMID 36826087, 2023). "We found that DLD, DLAT, PDHA1, and CDKN2A were differentially expressed between normal and tumor tissues; CDKN2A was upregulated and the other genes were downregulated in the tumor tissues." (PMID 37711156, 2023). "Difference analyses showed that 7 of 10 CRGs were dys-regulated in tumor samples compared with those in normal samples, among which LIPT1, PDHA1, GLS and CDKN2A were up-regulated, and FDX1, DLD and MTF1 were down-regulated." (PMID 37333810, 2023). "Cuproptosis, especially PDHA1, play a crucial role in the TIME characteristics, tumor progression, and long-term prognosis of NB." (PMID 38012558, 2023). "Specifically, the expression levels of SLC6A3, MITD1, and PDHA1 exhibited an increasing trend with tumor pathological stage, whereas CCS, LIPT2, PDHB, and PDHA1 displayed a decreasing trend in response to radiation therapy." (PMID 38159255, 2023). "CDKN2A, GLS, LIPT1, and PDHA1 were up-regulated in tumor samples, and FDX1, DLD, MTF1 were down-regulated in tumor samples." (PMID 36176287, 2022). "The results showed that, in tumor samples, ATP7B, PDHA1, and SLC31A1 were significantly upregulated compared with normal tissues, whereas ATP7A, DLST, GCSH, LIAS, and LIPT1 were significantly downregulated." (PMID 36567939, 2022). "We found that LIAS and CDKN2A were significantly upregulated in tumor samples, and FDX1, DLD, DLAT, PDHA1, PDHB, MTF1, and GLS were significantly downregulated in tumor samples." (PMID 36531222, 2022). "The expression of MTF1, NLRP3, and SLC31A1 was positively related with ImmuneScore, StromalScore, and ESTIMATEScore in almost all types of tumor, whereas ATP7B, DLAT, DLD, LIAS, PDHA1, and PDHB were significantly negatively correlated with the scores." (PMID 36387247, 2022). "In tumor cell-enriched region, the expression of COPS5, DLAT, DLD, FDX1, NFE2L2, PDHA1 and PDHB in the high score group is higher than that in the low score group, while the opposite is true for DLST, GCSH and LIPT2 (P <0.05)." (PMID 36618352, 2022). "Among them, 7 genes (DLAT, DLD, GCSH, LIAS, LIPT1, PDHA1, and PDHB) were upmodulated, whereas 3 genes (ATP7B, FDX1, and SLC31A1) were downmodulated in the tumor group in contrast with the normal group (p < 0.05)." (PMID 36046242, 2022). "In our result, augmented levels of PDHA1 were observed in the tumor tissues of CESC, CHOL, LIHC, LUAD, LUSC, STAD, and UCEC, whereas low expression of PDHA1 was observed in BRCA, GBM, KIRC, KIRP, PCPG, and THCA." (PMID 36003495, 2022). "PDHA1 inhibition affects PDHC activity, leading to tumor cell glycolysis, enhanced consumption of glucose and glutamine, and inhibition of oxidative phosphorylation." (PMID 35990673, 2022). "Downregulation of proteins involved in the mitochondrial respiratory chain like NFU1, ACO2, PDHA1, and proteins like DECR1, CNDP2, and SPINT1, which have a tumor suppressive role in different cancers were noted." (PMID 34885041, 2021). "Increased PDK activities are tumor suppressive, and PDC/PDHA1 activities are required for tumor growth." (PMID 34948229, 2021). "Lastly, we explored the relevance of our finding in two independent human tumour samples, and consistently with our predictions HLRCC tumours display increased abundance of PDHA1 S232 phosphorylation compared to adjacent normal kidney tissue." (PMID 29191787, 2018). "We found that knockdown of PDHA1 and MPC1 reversed the avidity of PGC1α overexpression cells for OXPHOS and blocked tumor cells migration and invasion mediated by PGC1α." (PMID 29700317, 2018).
tumor (continued). "The activity of PDHA1 is negatively regulated by pyruvate dehydrogenase kinase 1 (PDK1), which phosphorylates PDHA1 at the Ser232 residue, thereby facilitating a metabolic shift toward glycolysis—a phenomenon frequently observed in tumor cells." (PMID 41465397, 2025). "We found that five cuprotosis molecules, DLAT, PDHA1, FDX1, GLS and CDKN2A, were significantly different between paired tumour and adjacent non-tumour samples from the TCGA-STAD cohort, and LIAS, DLD, DLAT and MTF1 were significantly different among the four pathologic T categories 1–4." (PMID 36895378, 2023). "As expected, Ki67 and PDHA1 were expressed more strongly in the circRBM33-overexpressing tumour tissues than in the negative control tumours, while FMR1 was slightly altered." (PMID 37056926, 2023). "The results revealed that LIAS, DLAT, PDHA1, and CDKN2A were significantly upregulated in LUAD tumors compared to normal tissues, while ATP7B, SLC31A1, FDX1, MTF1, and GLS were significantly downregulated in tumor tissues." (PMID 36983664, 2023). "We found that PDHA1 was downregulated and CDKN2A was upregulated in the tumor samples." (PMID 37711156, 2023). "In high %GP4 tumours, PDHA1 was significantly lower compared to low %GP4 tumours, while LDHA/PDHA1 was significantly higher, which provides indirect evidence for a shift from oxidative to glycolytic metabolism associated with the emergence of a more glycolytic cell population." (PMID 35075123, 2022). "In addition, CDKN2A (p = 2e-24), DLAT (p = 8.8e-09), DLST(p = 0.00047), GLS(p = 2.5e-13) and PDHA1 (p = 8.3e-14) were significantly different at the in HCC patients with high tumor grades, low tumor grades and adjacent normal tissues." (PMID 36588699, 2022). "Genes and proteins regulating the TCA cycle (PDHA1, SUCLG2, SUCLG1, and IDH2) as well as mitochondrial function (VDAC1, MRPS31, LARS2, OPA1, and MTIF2) showed higher transcripts and protein levels in Wnt‐high compared with Wnt‐low tumor entities." (PMID 35904277, 2022). "The other five CRGs, including FDX1, SLC31A1, LIPT2, PDHA1 and GCSH, did not have any mutations in tumor samples." (PMID 36479114, 2022). "The 4T1 cells expressing si-PDHA1 and co-expressing PDHA1 S293A dephospho-mimetic, but not PDHA1 WT or PDHA1 S293D phospho-mimetic, had reduced xenograft tumor growth, as detected by tumor volume changes." (PMID 35740278, 2022). "We have detected a modest in vitro dependence on exogenous lipids in the cells with PDHA1 KO, but this does not appear to explain the essential role in model tumor growth." (PMID 34749809, 2021). "Likewise, CycT also strongly reduced the levels of pyruvate dehydrogenase (PDHA1) and glucose transporter SLC2A1 (GLUT1) in tumor cells." (PMID 30723259, 2019). "Although the expression was heterogeneous in these tumors, no single tumor was pure negative for the PDHA1 protein expression." (PMID 28076853, 2017). "Furthermore, we validated the effect of HBXIP on PDHA1, SCO2 or HIF1α in xenograft tumor tissues by Western blot analysis and IHC analysis, respectively." (PMID 26309161, 2015). "DLAT, DLD, PDHA1 and PDHB served as three vital subunits of PDC, which is the important component of the mitochondrial aerobic respiration process and played a key role in the cuproptosis process, and the expression levels of which were also believed to be related to tumor prognosis." (PMID 36882769, 2023). "As we found that LINC00273 was involved in EMT, which is critical for tumor cell migration, through ZEB1 expression, we focused on the LINC00273 gene expression as a representative of common genes that were regulated by the p-PDHA1/PKM2 complex in transcriptional level." (PMID 35740278, 2022). "Phosphorylation of PDHA1 on S232 is known to inhibit PDH activity and is also reported to be necessary for tumour growth, and thus, we hypothesised that IKKε regulates pyruvate entry in the TCA cycle and consequently electron provision for the respiratory chain." (PMID 32783398, 2020).
tumor (continued). "We found that FDX1, LIPT1, DLAT, PDHA1, PDHB, DLST, and ATP7A were significantly differentially expressed in tumor and nontumor tissues, with the standard of p < 0.05." (PMID 36975441, 2023).
cancer (74 papers, 2013 to 2025). A tumor composed of atypical neoplastic, often pleomorphic cells that invade other tissues. "Pyruvate dehydrogenase A1 (PDHA1) is a pivotal component of both the tricarboxylic acid cycle and glycolysis, and plays a significant role in cancer-associated metabolic processes." (PMID 41050056, 2025). "Reports have shown that a reduction in PDHA1 expression or activity is associated with unfavorable outcomes in multiple cancer types." (PMID 40090587, 2025). "In gastric cancer, increased PDHA1 expression is associated with a poor prognosis, while downregulation of this gene promotes cancer progression." (PMID 39702350, 2024). "Co-expression analysis revealed that PDHA1 was correlated positively with these cancer-associated pathway markers." (PMID 38012558, 2023). "The single-cell transcriptomic sequencing study suggested that PDHA1 expression was significantly associated with several cancer-associated signaling in LUAD, including cell cycle, DNA damage, and DNA repair." (PMID 36003495, 2022). "We also analyzed the potential association between PDHA1 gene expression and immune infiltration in 33 types of cancers." (PMID 36518756, 2022). "Prognostic analysis for OS, DSS, and PFS revealed that hypomethylation of DLAT, FDX1, MTF1, NLRP3, and PDHA1 was associated with low survival in most cancers, whereas hypermethylation of FDX1 and PDHB was associated with low survival in UVM(P < 0.05)." (PMID 36387247, 2022). "Mechanically, we used single-cell sequencing to discover that the PDHA1 expression had a close link with several cancer-associated signaling pathways, such as DNA damage, cell invasion, and angiogenesis." (PMID 36003495, 2022). "Second, more in vivo and in vitro studies about the underlying mechanisms of PDHA1 in cancer progression require further investigation." (PMID 36003495, 2022). "PDHA1 expression has been linked to cancer progression and metastasis." (PMID 39702350, 2024). "Therefore, the role of PDHA1 in pan-cancer was determined, and its association with known oncogenes and key checkpoints in cell cycle- and cell proliferation-related pathways in NB was also explored." (PMID 38012558, 2023). "Moreover, we evaluated the mutation diversity of PDHA1 in cancers and their association with prognosis." (PMID 36003495, 2022). "However, the underlying roles of PDHA1 methylation in various cancers remain largely unclear." (PMID 36003495, 2022). "Conversely, PDHA1 expression was found to be low across most cell populations, including cancer cells, fibroblasts and immune cells." (PMID 41050056, 2025). "Previously, SIRT3 was found to deacetylate lysine 321 (K321) of PDHA1 in cancer cells, K336 in skeletal muscle, and K83 in renal tubular epithelial cells and adipocytes." (PMID 41323268, 2025). "To explore the role of YBX1-dependent PDHA1 activation in cancer cells, we first examined the effect of pyruvate catabolism on cell growth using PDK inhibitors." (PMID 40812419, 2025). "The present study demonstrates that inhibition of the PDK/PDHA1 signaling axis results in metabolic and redox dysregulation within cancer cells, ultimately inducing apoptotic cell death." (PMID 41465397, 2025). "Cancer cells have been shown to undergo metabolic reprogramming when there is deregulation of the gene PDHA1, which has also been discovered." (PMID 41476448, 2025). "Inhibition of PDHA1 has been demonstrated to enhance the malignancy of cancer cells in previous studies." (PMID 41050056, 2025). "In cancer, PDHA1 is considered a central factor regulating the metabolic switch from oxidative phosphorylation to aerobic glycolysis." (PMID 38429887, 2024). "Pyruvate dehydrogenase E1 component subunit alpha (PDHA1) is a key gene involved in cuproptosis and consequently in the glucose metabolism reprogram of cancer cells." (PMID 39309446, 2024).